RNU4-58P (RNA, U4 small nuclear 58, pseudogene)
Gene: Small nuclear RNA gene on chromosome 16 (59,540,126 to 59,540,266, forward strand). Ensembl gene ENSG00000200062.
Homologues: Orthologues: chimpanzee U4 (99% identical), mouse Gm25899 (86% identical). Paralogues in human: RNU4-68P (88% identical), RNU4-7P (86% identical), RNU4-13P (85% identical), RNU4-67P (85% identical), RNU4-42P (84% identical), RNU4-8P (84% identical), RNU4-45P (83% identical), RNU4-23P (82% identical), RNU4-56P (82% identical), RNU4-76P (82% identical), RNU4-44P (82% identical), RNU4-92P (82% identical), and 81 more.